GSK3B (glycogen synthase kinase 3 beta)
Diseases named in the same sentence as GSK3B in open-access papers (continued):
Sharing a sentence is not in itself a finding about the gene and the disease.
glaucoma (7 papers, 2016 to 2025). Increased pressure in the eyeball due to obstruction of the outflow of aqueous humor. "Recent studies have shown a down regulation of the WNT/β-catenin pathway in glaucoma, associated with the overactivation of the GSK-3β signaling." (PMID 33925885, 2021). "Recent studies have shown a down regulation of the WNT/β-catenin pathway in glaucoma, associated with overactivation of the GSK-3β signaling." (PMID 33917605, 2021). "Overactivation of GSK-3β has been linked to neurodegenerative processes in glaucoma." (PMID 40683209, 2025). "The present work is a basic research showing that GSK-3β is a potential novel therapeutic target for maintaining the function of bleb after glaucoma filtration surgery." (PMID 34940783, 2021). "Further studies are needed to assess the potential of a GSK-3β inhibitor as a new treatment tool for increasing the success rate of glaucoma surgery." (PMID 34940783, 2021). "We compared the levels of fibronectin, collagen Iα, α-SMA, and GSK-3β between tenon tissues in normal subjects and patients with glaucoma." (PMID 34940783, 2021). "Recent studies have observed that glaucoma patients presented an activation of the GSK-3β pathway and its downregulation may be an interesting therapy target." (PMID 33925885, 2021). "Recent studies have observed that glaucoma patients present an increased GSK-3β activity and thus its inhibition could be an interesting treatment." (PMID 33917605, 2021). "Stimulating the WNT/β pathway, through the inhibition of GSK-3β, lithium, could be an innovative therapeutic way in glaucoma." (PMID 33925885, 2021). "While inhibitors of GSK-3β have been identified as an important strategy for the treatment of CNS disorders including AD, to date, there are few studies investigating whether these molecules could be of benefit for the treatment of glaucoma." (PMID 27544758, 2016). "Research indicates that cannabinoids influence several pathways related to glaucoma: Endocannabinoid System (ECS), WNT/β-Catenin Pathway, and Glycogen synthase kinase-3 beta (GSK-3β) Signaling." (PMID 40683209, 2025). "To determine the signaling pathway involved in EPO-mediated phosphorylation of NRF2 in glaucoma, we assessed the ratio of phosphorylated to total PI3K, Akt, JNK, STAT1, STAT3, GSK3β, and MAPK." (PMID 36978804, 2023). "Our results demonstrated the effect of GSK-3β inhibition on the regulation of TGF-β–mediated fibrosis of HTFs, suggesting GSK-3β to be a potential target for maintaining bleb function after glaucoma filtration surgery." (PMID 34940783, 2021). "At the same time, it is postulated that GSK-3β inhibitors such as CHIR 99021 would be effective in regulating bleb fibrosis, taking into account the elevated level of GSK-3β in patients with glaucoma." (PMID 34940783, 2021). "In the retina, an RNAi screen has recently identified GSK-3β as a regulator of Drp-1, inhibition of which was recently observed to preserve RGC axon integrity in murine glaucoma models." (PMID 27544758, 2016). "Although not statistically significant, the mRNA expression of GSK-3β was also elevated in patients with glaucoma." (PMID 34940783, 2021). "However, to the best of our knowledge, no study targeting GSK-3β has been performed in the context of preventing excessive bleb fibrosis after glaucoma filtration surgery." (PMID 34940783, 2021). "In addition, the GSK-3β level in the tenon tissue of patients with glaucoma also showed an increase, although it was not statistically significant." (PMID 34940783, 2021).
laryngeal carcinoma (7 papers, 2017 to 2026). Carcinoma that arises from the laryngeal epithelium. "ATRA enhances the suppressive role of RARα on miR-27a promoter and release the inhibition of miR-27a on GSK-3β leading to laryngeal cancer differentiation through GSK-3β-involved Wnt/β-catenin pathway." (PMID 28122350, 2017). "The GSK-3β gene was significantly knocked down at both mRNA and protein levels in laryngeal cancer cells transfected with si-GSK-3β compared to the control, which means the GSK-3β gene is successfully silenced by its small interference RNA." (PMID 28122350, 2017). "In addition, it has been illustrated that GSK-3β is a direct target of miR-632 in laryngeal carcinoma cells." (PMID 32024815, 2020). "Whether GSK-3β is a mediator in miR-27a-regulated differentiation of laryngeal cancer cells induced by ATRA is also a problem." (PMID 28122350, 2017). "In fact, glycogen synthase kinase-3 beta (GS3KB), which is involved in the Wnt/β Catenin pathway, has also been reported to be an miR-632 target in the laryngeal carcinoma." (PMID 37894814, 2023).
lymph node metastasis (7 papers, 2008 to 2022). "By comparing with clinical and pathologic characteristics, tumor GSK3β expression was significantly correlated with venous invasion of tumor cells and with the presence of lymph node metastasis." (PMID 32678196, 2020). "Advanced tumors with lymph node metastasis were characterized by high levels of S276p-NFκB (100%, p = 0.05) and S9p-GSK3β (100%, p = 0.05)." (PMID 18254976, 2008). "High DISC1 expression was correlated with smoking status (P=0.049), tumor size (P=0.013), pathology grade (P<0.001), grade (P=0.020), lymph node metastasis (P=0.032), and Ki-67 (P<0.001), p-GSK3β (P<0.001), β-catenin (P<0.001), and Cyclin D1 expression (P<0.001)." (PMID 29029423, 2017). "However, GSK-3β expression was not correlated with TNM tumor staging or lymph node metastasis." (PMID 29793508, 2018).
neuropathy (7 papers, 2014 to 2025). A disorder affecting the nervous system that manifests with pain, tingling, numbness, and/or muscle weakness. "The present study indicated the crucial role of GSK3β in some neuronal changes, including apoptosis in the lumbar section of the spinal dorsal horn following neuropathy, for the first time." (PMID 32483472, 2020). "The present study examined the potential effects of MAPT haplotype, expression levels, and GSK-3β mediated tau phosphorylation on the development of paclitaxel-induced neuropathy in vivo." (PMID 25535399, 2014). "A study that assessed inhibition of glycogen synthase kinase 3beta activity with lithium prevents and attenuates paclitaxel-induced neuropathy pain showed that lithium could prevent neuropathic pain from Taxol consumption through inhibiting GSK3B." (PMID 34819131, 2021). "Thus, this study attempted to evaluate the contribution of the p-GSK-3β/t-GSK-3β ratio in neuropathy-induced apoptosis in the spinal cord and the effect of the GSK-3β selective inhibitor, ARA014418, on the protection of spinal cord neurons from apoptosis." (PMID 32483472, 2020).
thyroid cancer (7 papers, 2017 to 2025). "Our detailed experiments depict a novel mechanism which is TRIM47 promoted the development of thyroid carcinoma via ADAR-associated ubiquitination, and GSK-3β mediated phosphorylation on both/either TRIM47 and ADAR was critical for TRIM47 suppression." (PMID 40618019, 2025). "This forms a feedback loop in which TET1 promotes thyroid cancer progression via the CK2/AKT/GSK3β/HIF1α signaling pathway." (PMID 37020036, 2023). "Surprisingly, we find that STAG2 knockdown makes BRAF-mutant thyroid cancer cells more sensitive to glutamine deprivation or glutaminase inhibitor via the ERK/AKT/GSK3β/c-Myc feedback axis." (PMID 37479689, 2023). "Since GSK-3β has different activities in different cell backgrounds, its activity state may be different in different subtypes of thyroid cancer." (PMID 40618019, 2025). "Mechanistically, knocking down STAG2 in BRAF-mutant thyroid cancer cells decreases the protein stability of c-Myc via the ERK/AKT/GSK3β feedback pathway, thereby impairing glutamine metabolism of thyroid cancer cells by down-regulating its downstream targets such as SCL1A5, GLS and GLS2." (PMID 37479689, 2023). "Contrastingly, GSK-3β overexpression was able to promote ADAR ubiquitination and further weaken the stability of ADAR in differentiated thyroid carcinoma FTD-133 cells." (PMID 40618019, 2025). "Specifically, ERK cascade is overactivated when STAG2 is down-regulated in thyroid cancer cells, followed with suppression of HER3 transcription and RAS signaling to promote protein degradation of c-Myc via AKT/GSK3β signaling pathway." (PMID 37479689, 2023). "The results of western blot analysis showed the phosphorylation of GSK3β was suppressed by NVP-BEZ235, accompanied by the kinase of GSK3β increased in all the four human thyroid cancer cell lines." (PMID 32025215, 2020). "The kinase activity assay demonstrated that silencing of IGFBP7 in various thyroid cancer cells markedly promoted, whereas overexpression of IGFBP7 suppressed, endogenous AKT activity, as demonstrated by the phosphorylation levels of a common AKT substrate, GSK3β." (PMID 31183073, 2019).
adenoma (6 papers, 2003 to 2024). A neoplasm arising from the epithelium. "Pharmacological inhibition of FAK/PYK2 repressed adenoma formation in APCmin/+ mice and reduced intestinal levels of phospho-GSK3β and β-catenin, indicating that the FAK/PYK2/GSK3β axis is critical in APC-driven intestinal tumorigenesis." (PMID 33266025, 2020). "Pharmacological inhibition of FAK/PYK2 repressed adenoma formation in APCmin/+ mice and reduced phospho-GSK3β and β-catenin intestinal levels, decreasing Wnt signaling." (PMID 33266025, 2020). "The immunoreactivity of the GSK3β protein in adenoma was significantly lower in the CRC and in the adjacent non-neoplastic mucosa (p=0.03 and p=0.0005, respectively)." (PMID 27462886, 2016). "The expression of β-catenin and GSK3β was analysed by immunoblotting in normal ovaries, benign adenomas, borderline tumours and adenocarcinomas." (PMID 14520463, 2003). "In the present study, we found a significant increase of β-catenin and GSK3β in the adenocarcinomas as compared to normal ovarian tissue and benign adenomas." (PMID 14520463, 2003). "Indeed, multiplex immunofluorescence staining of CRC patient and APCMin/+ mouse adenoma tissues showed that Axin and GSK3β or Axin and CK1α exhibited fewer colocalized regions than those of the controls." (PMID 38279052, 2024). "They hypothesized that a prolonged stimulation of principal cell proliferation by lithium, via its inhibition of the enzyme glycogen synthase kinase 3 beta and the increased availability of β-catenin in tubular cells can eventually induce adenomas and carcinomas." (PMID 30079440, 2018). "Avaliar o complexo de destruição da betacatenina no carcinoma colorretal e no adenoma do colo pela expressão das proteínas betacatenina, adenomatous polyposis coli, GSK3β, axina e ubiquitina." (PMID 27462886, 2016).
brain tumors (6 papers, 2014 to 2021). "To preliminarily test this supposition, we employed the irreversible Gsk3β inhibitor tideglusib, a drug in several clinical trials for its effects on stem cells and that has shown antiproliferative and antitumorigenic effects on brain tumors." (PMID 31001473, 2019). "Overall, our results suggest that SIRT1 and AROS inhibit GSK3β activity and provide a basis for the mechanism of DOX efficacy in brain tumor chemotherapy." (PMID 32158616, 2020).
glomerular diseases (6 papers, 2015 to 2025). "Recent studies have extended the pathogenic scope of GSK3β beyond lipopolysaccharide (LPS)- or adriamycin-induced models to other glomerular diseases relevant to human pathology." (PMID 40526103, 2025). "Recent evidence suggests that some podocytopathic signaling mediators, such as GSK3β, are implicated in podocyte injury and glomerular disease." (PMID 35721571, 2022). "In addition to the regulation of NRF2-mediated antioxidant response, podocyte cytoskeleton integrity and MPT, GSK3β plays a pivotal role in the canonical Wnt/β-catenin signaling pathway which has been recently implicated in primary glomerular disorders." (PMID 40526103, 2025). "Therefore, the use of highly selective GSK3β inhibitors or lithium at low doses presents a promising therapeutic approach for the treatment of glomerular diseases." (PMID 40526103, 2025). "Collectively, GSK3β-directed fine-tuning of NF-κB might serve as a novel therapeutic target for glomerular disease." (PMID 40526103, 2025). "In consistency, as shown by immunoblot analysis of isolated glomeruli, ecdysone-triggered albuminuria and early signs of glomerulopathy were concomitant with reduced glomerular expression of GSK3β with inhibitory phosphorylation of at serine 9, indicative of GSK3β hyperactivity." (PMID 30111886, 2018). "A growing body of evidence provides comprehensive data on GSK3β’s functions across various kidney diseases, such as DKD, PKD, and glomerular diseases, with a focus on its impact on inflammatory responses, fibrotic transformation, and oxidative stress." (PMID 40526103, 2025).
glomerulosclerosis (6 papers, 2015 to 2025). A hardening of the kidney glomerulus caused by scarring of the blood vessels. "Combined knockout (KO) of both GSK3α and GSK3β specifically in glomerular podocytes in embryonic or adult mice caused severe podocyte injury, glomerulosclerosis, and heavy proteinuria." (PMID 35166234, 2022). "Moreover, glomerular expression levels of GSK3β also correlated positively with the severity of glomerulosclerosis but negatively with eGFR." (PMID 35166234, 2022). "Moreover, glomerular expression levels of GSK3β correlated with the severity of glomerulosclerosis and with serum creatinine." (PMID 35166234, 2022). "Accumulating evidence indicates that GSK3β is aberrantly activated in injured renal parenchymal cells, where it exacerbates CKD by promoting fibrogenesis, glomerulosclerosis, and tubulointerstitial damage." (PMID 40526103, 2025). "Furthermore, treatment of HMC cells with the GSK3β inhibitor CHIR99021 (activator of Wnt signalling) abrogated the inhibitory effects of cyclin G2 on canonical Wnt signalling and glomerulosclerosis-related proteins." (PMID 30420966, 2018).
glucose metabolism disorders (6 papers, 2016 to 2025). "This research initially demonstrated the multi-targeted approach of polysaccharide degradation by Noni juice, which can replicate the combined effects of “Nrf2 activators and GSK3β inhibitors” to enhance insulin sensitivity and mitigate glucose metabolism disorders." (PMID 40941105, 2025). "ameliorates insulin sensitivity and glucose metabolism disorders by regulating the IRS1/PI3K/AKT signaling pathway and the expressions of its downstream targets GLUT4, FOXO1, and GSK3β." (PMID 40351361, 2025).
Hyperinsulinemia (6 papers, 2015 to 2023). An increased concentration of insulin in the blood. "Taken together, our findings suggest that C-peptide is an antideciduogenic factor acting via the regulation between PP1 and GSK3β in patients with hyperinsulinemia." (PMID 33330513, 2020). "In addition, treatment with caffeic acid helped to improve memory ability by maintaining synaptic activity by regulating glycogen synthase kinase-3 beta (GSK-3β) and tau protein expression and Aβ levels in the hippocampus of high-fat diet-induced hyperinsulinemia rats." (PMID 37762386, 2023). "For instance, AKT-2, GSK-3β, GLUT1, and GLUT4 mRNA expression were upregulated in the hearts of hyperinsulinemic horses, suggesting that prolonged hyperinsulinemia induced an increase in insulin sensitivity in the heart, which could be cardioprotective." (PMID 32596266, 2020). "Moreover, uncontrolled expression of lipogenesis and gluconeogenesis (as shown by up-regulation of SREBP1c, GSK3β phosphorylation and PEPCK, respectively) in the face of hyperinsulinemia and hyperleptinemia, further exacerbates diabetic dyslipidemia upon prolonged HFHS dieting." (PMID 25658428, 2015).
mental disorder (6 papers, 2013 to 2025). A disease that has its basis in the disruption of mental process. "TAAR1 has been found to heterodimerize with the dopamine receptor 2, which is thought to silence glycogen synthase kinase 3 beta (GSK3β) implicated in various mental disorders." (PMID 32486277, 2020). "This agent has been used to treat mental disorders, but considering its inhibition of GSK3b 38,39,40,41, LiCl induces WNT pathway activation." (PMID 41294202, 2025). "In the present review, the emerging role of a new set of risk genes (DISC1, GSK3β, and TRAX) for mental disorders in the repair of oxidative DNA damage will be discussed." (PMID 30285728, 2018). "Lithium, a clinical mood stabilizer for mental disorders, potently inhibits the activity of glycogen synthase kinase 3β (GSK3β) that promotes the ubiquitin-dependent proteasome degradation of GLI1, an important downstream component of hedgehog signaling." (PMID 23626687, 2013). "Further understanding of when and where the DISC1/TRAX/GSK3β complex is formed and how the complex can be effectively dissembled by either GSK3β inhibitors or PKA activators (such as A2AR agonists or PDE4 inhibitors) would pave the way for developing new therapeutic agents for mental disorders." (PMID 30285728, 2018).
myotonic dystrophy type 1 (6 papers, 2019 to 2025). Steinert disease, also known as myotonic dystrophy type 1, is a muscle disease characterized by myotonia and by multiorgan damage that combines various degrees of muscle weakness, arrhythmia and/or cardiac conduction disorders, cataract, endocrine damage, sleep disorders and baldness. "However, inhibition of GSK3β prevents muscle atrophy in mice and guinea pigs, and it further prevents development of myotonic dystrophy type 1 (DM1), eventually leading to skeletal muscle being characterized by higher fiber density, and normal fiber size." (PMID 32851594, 2020).
pheochromocytoma (6 papers, 2018 to 2025). "Previous studies have shown that the increased expression of AKT phosphorylation in pheochromocytoma 12 cells can cause an increase in GSK‐3β phosphorylation levels." (PMID 37990376, 2023). "Supratherapeutic concentrations of lithium decrease the activity of glycogen synthase kinase-3β (GSK-3β), leading to cell cycle arrest in several in vitro cancer models including medullary thyroid cancer (TC), pheochromocytoma/paraganglioma and carcinoid." (PMID 31750236, 2019). "Altogether with another study used insulin treatment in a cloned rat pheochromocytoma cell lines showed that increase in the p-GSK-3β (Ser9) levels agreed roughly with the repression in p-GSK-3β (Tyr216) because insulin activate Akt, an inhibitor for ERK1/2 as well as GSK-3β (Tyr216)." (PMID 40381124, 2025). "GSK-3β regulated radiosensitivity through miR-21, high miR-21 levels has a negative correlation with low GSK-3β levels in different human tumors (pheochromocytoma/paraganglioma, kidney tumor and testicular germ cell tumors)." (PMID 29793508, 2018).